LEP (leptin)
Diseases named in the same sentence as LEP in open-access papers (continued):
Sharing a sentence is not in itself a finding about the gene and the disease.
Obesity (continued). "However, although it is not yet possible to target the primary lesion, an alternative strategy for treating obesity would be modulating the activity of neurons regulating feeding that are downstream of the site(s) of leptin resistance." (PMID 36411386, 2022). "LEP is a multifunctional hormone secreted from adipocytes, linking obesity to BC, and may play important roles in BC development." (PMID 35965527, 2022). "In addition, in the case of obesity, the imbalance of inflammatory cytokines and the consequent high levels of circulating leptin together with a condition of leptin resistance, can also affect the birth itself." (PMID 35458224, 2022). "Thus, to develop an effective obesity therapy based on leptin, the prevention of leptin resistance is a vital challenge." (PMID 36009315, 2022). "However, these approaches have failed due to impaired leptin function in obesity and its diverse regulation in various organs and tissues." (PMID 35745267, 2022). "Moreover, ghrelin, in combination with leptin and orexin, has been attributed a role in the development of obesity in people with short sleep duration." (PMID 35627229, 2022). "With obesity, greater secretion of pro-inflammatory adipokines (including leptin, IL-6, TNF-α, and resistin) was observed, affecting satiety and lipid metabolism, along with a decrease in anti-inflammatory and insulin-sensitizing cytokines such as adiponectin and IL-10." (PMID 36364915, 2022). "Thus, L. reuteri treatment during pregnancy ameliorates HF diet-related obesity through a leptin-independent pathway." (PMID 36235659, 2022). "Thus, in contrast to leptin, obesity appears to have an inverse relationship with adiponectin levels in obese dogs." (PMID 36262532, 2022). "Finally, activation of the leptin-aldosterone-neprilysin axis appears to contribute importantly to the natural evolution of HF in T2DM patients with obesity and NT-proBNP levels require more thorough evaluation to predict HFpEF." (PMID 35050233, 2022). "Consequently, reversing leptin resistance or increasing leptin sensitivity has been a consideration to combat obesity." (PMID 35323110, 2022). "Possible biological explanations for the associations between vascularproblems and poorer sleep quality are the altered levels of leptin and ghrelin,making way for obesity and hormonal changes, such as increased cortisol levelsresulting from inadequate or insufficient sleep." (PMID 35730889, 2022). "This raises the possibility that Fetuin B may be triggered by signals from expanding adipose tissue in obesity, such as, leptin." (PMID 35896788, 2022). "To conclude, it is still not known whether the impact of leptin on the myocardium in the course of obesity results from hyperleptinemia or leptin resistance; therefore, further studies are required." (PMID 35457013, 2022). "The adipose tissue hormone adiponectin, unlike leptin, correlates inversely with obesity and its secretion is stimulated by fat loss." (PMID 36499772, 2022). "Interestingly, the obesity‐related leptin dose not only elevated Th2 and Th17 cytokine levels, but also directly reduced the Treg function in CD4+ T cell cultures from lean AA patients." (PMID 35734271, 2022). "The change of IL-6 as a dependent variable was affected by IL-12, dopamine, and leptin as independent or predictor variables, and the change of leptin as a marker of obesity was greatly affected by both pro-inflammatory cytokines (IL-6 and IL-12, serotonin, and body weight." (PMID 36364892, 2022). "Given that CRISPR-mediated deletion of Lepr in adult AGRP neurons causes hyperphagia, obesity, and diabetes, we hypothesized that TET3 might affect leptin signaling in AGRP neurons." (PMID 36189793, 2022). "Apart from leptin, there are several other adipokines and factors which include hepatokines and myokines that are related with obesity and are affected by BS such as adiponectin, Insulin-Like Growth Factor Binding Protein 2, sex hormone-binding globulin and fetuin A." (PMID 35328759, 2022).
Obesity (continued). "Moreover, 98.2% of the change in leptin is due to the changes in IL-6, IL-12, serotonin, and BW as markers of inflammation, brain chemistry, and obesity respectively." (PMID 36364892, 2022). "Although their contribution to leptin expression has not been reported, Plagl1, Cdkn1c, and Kcnq1ot1 have been found to be involved in adiposity and obesity, implying that they may impact leptin expression in the adipose tissue." (PMID 36618698, 2022). "It is well known that hypothalamic inflammation reduces the responsiveness of POMC and NPY neurons in the ARC to the physiological actions of leptin and insulin and alters the normal activity of the orexigenic and anorexigenic peptides, thereby promoting energy imbalance and obesity." (PMID 35683029, 2022). "Leptin concentrations reflect the amount of body fat that may be decreased in anorexia or increased in obesity." (PMID 36186778, 2022). "Similarly, high serum leptin levels have been found, in asthmatic mice with obesity, to promote allergic airway inflammation in preclinical models." (PMID 36613991, 2022). "Our study suggests that adipokines such as PENK, IGF-1, chemerin, AGF, AFABP and leptin might affect the development of obesity by directly modifying individual eating behavior." (PMID 34636987, 2022). "This correlation was strengthened in obesity, which reinforces the hypothesis that leptin resistance is involved in depression." (PMID 36430254, 2022). "High leptin content under obesity leads to cartilage degeneration." (PMID 35354886, 2022). "Leptin is a marker of fat reserves and circulating levels are high in obesity." (PMID 36173650, 2022). "It is well known that obesity would reduce adiponectin levels and increase leptin levels." (PMID 36079890, 2022). "It has led to the hypothesis that obesity is a state of “leptin resistance” in which an excess of serum leptin is present." (PMID 35886710, 2022). "Ghrelin suppresses insulin secretion by regulating uncoupling protein 2 (UCP2) in panarctic β cells; ghrelin ablation attenuates hyperglycemia of leptin-deficient ob/ob mice without affecting obesity." (PMID 35454071, 2022). "However, in rodent models of obesity, leptin can be transported completely across the BBB in the absence of functional ObRs." (PMID 36131285, 2022). "In leptin-resistant states (due to high leptin concentrations as may occur in obesity), ARC KP-neurons are quiescent inhibiting reproduction." (PMID 36479214, 2022). "In addition to leptin’s main role in obesity, mostly referring to body weight regulation and energy homeostasis, it plays a major role in CRC by stimulating proliferation and inhibiting apoptosis." (PMID 35563103, 2022). "Leptin has also been used in clinical trials exploring therapeutic potential in obesity." (PMID 35844529, 2022). "The conceptualization of leptin as a regulator of body weight fits perfectly into the Set-Point theory and was overwhelmingly accepted by the vast majority of researchers including those working in the field of obesity." (PMID 35662925, 2022). "Both the LEP G2548A and LEPR Q223R variants were related to the increase in obesity risk." (PMID 36551995, 2022). "A recent review suggested that obesity increases susceptibility to SARS-CoV-2 infection due to changes in immune pathophysiology, including the increased production of pro-inflammatory cytokines, adipokines, and leptin." (PMID 35666734, 2022). "Resistance to leptin action in obesity has been suggested, and elevated circulating concentrations may be necessary to maintain sensitivity to hormone and energy homeostasis." (PMID 36466401, 2022). "Although leptin was originally considered an anti-obesity hormone because of its regulatory role in the maintenance of body weight, there is growing evidence supporting the significant influence leptin exerts on both glycemic control and cognitive function as well." (PMID 35527735, 2022).
Obesity (continued). "No XRN1 variants in humans have been associated with obesity, but a recent study investigating forebrain-specific Xrn1 knockout mice found that lack of Xrn1 in neurons led to obesity, hyperphagia, leptin resistance and hyperglycemia." (PMID 35330733, 2022). "Additionally, this study identified baseline leptin and adiponectin levels as independent predictors of post-treatment weight gain in children with (previous) obesity." (PMID 35769076, 2022). "That said, clinical trials exploring whether the apparent antagonistic relationship between leptin and fat storage may be utilized as treatment for obesity by recombinant leptin administration yielded disappointing results." (PMID 35269504, 2022). "Therefore, the present study investigated the activities of and mechanisms by which YHIEPV increases leptin sensitivity to exert its anti-obesity effects." (PMID 35597815, 2022). "Furthermore, sleep disorders decrease carbohydrate tolerance, alter leptin and cortisol levels, thus modifying insulin sensitivity and favouring obesity and MS." (PMID 35896655, 2022). "Further, obesity appears to worsen autoimmune disorders in a number of incompletely understood ways, including promoting autoantibody production and secretion of adipokines such as leptin that promote inflammation." (PMID 35874527, 2022). "We previously demonstrated the protective anti-obesity effects of perinatal leptin administration." (PMID 35684076, 2022). "While lean or leptin-deficient animals are responsive to the anorectic and weight-reducing effect of leptin, diet-induced obesity manifests itself as a leptin-resistant state where hyperleptinemia is accompanied by lack of response to exogenous leptin administration." (PMID 35323110, 2022). "In both obesity and type 1 diabetes, leptin, resistin, and β-cell autoimmunity are elevated, but it is not clear yet if obesity accelerates or causes type 1 diabetes." (PMID 36147568, 2022). "It suggests that hyperleptinemia may be a driving force for obesity, as chronic treatment with exogenous leptin that exceeds the individual’s required limit significantly increases body weight." (PMID 35628271, 2022). "In the long term, developing treatments that effectively alleviate leptin resistance may benefit patients with atypical depression characterized by obesity-related metabolic alterations." (PMID 36430254, 2022). "In addition, the present review aimed to investigate the involvement of leptin in physical exercise and its relevance in the control of obesity, especially in the child population." (PMID 36499740, 2022). "Furthermore, this study supports the theory that both leptin and ghrelin play substantial roles in the development of hyperinsulinemia and IR in individuals with obesity." (PMID 36203073, 2022). "Moreover, leptin, a possible key mediator linking obesity to OA, modulates the degradative functions of the chondrocytes through the upregulation of MMP9 and −13." (PMID 35329213, 2022). "The link between obesity, leptin, and AD is now well established and has been extensively studied." (PMID 35563589, 2022). "It has been suggested that leptin resistance in obesity might start through the activation of inflammatory signalling." (PMID 35563589, 2022). "Most genetic rodent models of obesity are based on the disruption of the leptin signaling pathway." (PMID 35505192, 2022). "In addition to energy storage, adipose tissue functions as an endocrine organ releasing various adipokines (e.g., leptin and adiponectin) with a wide range of physiological effects on obesity-related symptoms." (PMID 35967777, 2022). "The insulin receptor itself is also known to contribute to cell function, although whether T cells become insulin or leptin-resistant with long-standing obesity is still unclear." (PMID 35406000, 2022). "Leptin is a pleiotropic hormone produced primarily by adipose tissue and in part by skeletal muscle and the stomach, and plays a critical role in the development of obesity." (PMID 35162142, 2022).
Obesity (continued). "Conversely, leptin can have directly pro-inflammatory roles in obesity and may sensitize macrophages with increased potential to drive inflammation." (PMID 35039633, 2022). "Excess circulatory leptin levels, along with defective leptin receptor signaling, could lead to leptin resistance, which further aggravates obesity, allowing for the initiation of a vicious positive feedback loop." (PMID 35628271, 2022). "The present study describes associations between SNPs in leptin pathway genes, revealing positive and negative interactions between reported SNPs and the clinical markers related to obesity in a sampled Mexican population." (PMID 35741707, 2022). "PI3K was also suggested by the results of IPA to be a target molecule in leptin signal in obesity." (PMID 36065413, 2022). "Obesity in mammals has an influence on thermoregulation in different ways, increasing the thermal insulation conferred by subcutaneous fat, reducing motor activity, as well as modifying endocrine thyroidal metabolism and leptin signaling." (PMID 35990356, 2022). "We could only speculate regarding the reason as to why n-9 fatty acids were negatively correlated with leptin gene expression in visceral adipose in obesity, or regarding the interaction between different fatty acids." (PMID 35215564, 2022). "Leptin and adiponectin are crucial adipokines that are in a state of imbalance in obesity." (PMID 36366375, 2022). "Several mechanisms have been proposed to link obesity and depression, including a mild level of chronic inflammation characteristic of obesity, chronically increased proinflammatory interleukin (IL-2) levels, and leptin signaling." (PMID 36615803, 2022). "Our results demonstrated that obesity with leptin deficiency or leptin receptor deficiency does not stimulate endometriosis development." (PMID 36140261, 2022). "This increase may be secondary to an increase in leptin, often elevated in obesity, leading to increased CD8+ T cells and STAT3, which is both a signal transducer and activator of transcription." (PMID 35326592, 2022). "Increased levels of leptin in individuals living with obesity coupled with the ability of B cells to perceive the adipokine suggest that it may be one of the regulators of the pro-inflammatory/regulatory B cell balance." (PMID 35960996, 2022). "Adiponectin is inversely correlated with age and obesity and counteracts the effect of leptin." (PMID 35371597, 2022). "Comprehending how leptin regulates adipose tissue may provide important clues to understand the pathophysiology of obesity and related diseases, such as type 2 diabetes, as well as its prevention and treatment." (PMID 34523036, 2022). "However, obesity promotes insulin resistance and increases serum insulin levels, and high insulin levels increase leptin levels, eventually leading to leptin resistance in the nervous system and adipose tissue." (PMID 36557203, 2022). "However, majority patients with obesity show higher leptin levels due to the development of hypothalamic leptin resistance." (PMID 35909571, 2022). "Obesity-induced increases in serum leptin levels have also been shown to skew bifurcation of leptin receptor (LEPR) expressing skeletal stem/progenitor cells (SSPCs), which function as precursors of bone and fat in adult bone marrow, toward adipogenesis at the expense of osteogenesis." (PMID 36138736, 2022). "Obesity is related to the high level of leptin, as well as the anorectic resistance of leptin." (PMID 36551211, 2022). "In this paper, we show that TNP administration after onset of HFD feeding protects mice from DIO and obesity-induced bone loss under thermo-neutral conditions by preventing HFD-induced increases in body weight, body fat mass, serum leptin levels and MAT volume." (PMID 36138736, 2022).
Obesity (continued). "Obesity results in pathological states of low‐grade chronic inflammation with increased production of proinflammatory cytokines, such as interleukin‐6 (IL‐6), tumor necrosis factor‐α, interleukin‐ 1b (IL‐1b) and leptin." (PMID 35398917, 2022). "It was proposed that hyperinsulinemia favors obesity, contributing to a higher increase in leptin." (PMID 36289903, 2022). "Leptin signaling is active in Ay/a mice that demonstrate a delayed onset in obesity." (PMID 35782067, 2022). "The graphs are suggestive in illustrating the obesity-leptin connection." (PMID 35989732, 2022). "Nervonic acid was also reduced along with a reduction in body weight in obese women and may have protective effects in obesity-related metabolic risk factors such as lipid levels, fasting blood glucose, CRP and leptin." (PMID 36140306, 2022). "In addition to links to obesity, neurological evidence suggests that both ghrelin and leptin can modulate neural responsiveness to food rewards." (PMID 35634372, 2022). "During obesity, the serum leptin concentration increases, which can result in a leptin resistance." (PMID 35844529, 2022). "Elevated leptin, insulin and lipid levels are features of obesity, each of which might also contribute to differences in cardiovascular development in the next generation." (PMID 36346818, 2022). "It was reported for the first time that P. atlantica leaf methanol extract and its sub-extracts did not have a significant effect against the PTP1B enzyme, which has an essential role in diabetes and obesity and is a negative regulator of leptin and insulin signaling pathways." (PMID 35281888, 2022). "Leptin also acts as an important factor in the pathogenesis of obesity-related cardiac remodeling." (PMID 36531958, 2022). "The shift in equilibrium can lead to leptin resistance and obesity state." (PMID 35480480, 2022). "Furthermore, we previously demonstrated that the genetic deletion of Rap1 in forebrain neurons protected mice against HFD-induced obesity and decreased leptin responsiveness." (PMID 35597815, 2022). "Homocysteine may ameliorate the leptin signaling pathway by inhibiting JAK-STAT signaling that is regulated by the obesity hormone, leptin." (PMID 36512575, 2022). "Our study suggests that adipokines such as pro-enkephalin, IGF-1, chemerin, AGF, AFABP and leptin may affect obesity by directly controlling eating behavior (expressed as disinhibition, cognitive restraint and hunger)." (PMID 34636987, 2022). "The link between leptin and dental pulp/periapical defensive and reparative responses could provide new evidence of the relationship between obesity, inflammation and oral infections." (PMID 35216099, 2022). "Moreover, melatonin is used as a therapeutic agent against obesity, obesity-induced leptin resistance, diabetes mellitus, hepatic steatosis, and myocardial injury." (PMID 35624703, 2022). "Moreover, the interactions between the genetically acquired and inherited variation in LEP related to obesity, the gut microbiome, and CRC still require investigation to provide new insights yielding novel medical approaches." (PMID 35563103, 2022). "Obesity affects thermoregulation in different ways, i.e., by thermal insulation of enhanced subcutaneous fat, low heat production due to reduced motor activity, endocrine dysregulation, i.e., thyroid and leptin resistance." (PMID 35990356, 2022). "Finally, we studied the predictive ability of leptin and adiponectin on weight outcomes during and after obesity treatment." (PMID 35769076, 2022). "Leptin plays a major role in the chronic inflammation found in patients with obesity." (PMID 35795152, 2022). "Hyperphagia, hyperinsulinemia, and decreased sympathetic outflow are observed in mice with disruption of the leptin gene (ob/ob) as well as in mice and rats with genetic disturbances of LepR signaling (db/db and fa/fa, respectively), and lead to early onset obesity." (PMID 35163521, 2022).